ZDHHC20P2 (ZDHHC20 pseudogene 2)
Synonyms: OTTHUMG00000133740
Gene: Processed pseudogene on chromosome 6 (31,380,411 to 31,380,839, forward strand). Ensembl gene ENSG00000223702.
Diseases named in the same sentence as ZDHHC20P2 in open-access papers:
ZDHHC20P2 is named in the same sentence as 1 disease in open-access papers, as found by Europe PMC text mining. Sharing a sentence is not in itself a finding about the gene and the disease. The quoted sentences say what the papers report.
cancer (1 paper, 2025). A tumor composed of atypical neoplastic, often pleomorphic cells that invade other tissues. "rs4143334, in the noncoding transcript exon of ZDHHC20P2 increased cancer risk (OR (95% CI) = 1.89 (1.51, 2.35), pmeta = 1.91 × 10−8)." (PMID 41038832, 2025).